TTN (titin)
Diseases named in the same sentence as TTN in open-access papers (continued):
Sharing a sentence is not in itself a finding about the gene and the disease.
cerebral palsy (2 papers, 2018 to 2024). A group of disorders affecting the development of movement and posture, often accompanied by disturbances of sensation, perception, cognition, and behavior. "In fascioscapulohumeral muscular dystrophy (FSHD) titin-based stiffness is increased and in cerebral palsy patients, an increase in titin-based passive stiffness has been implicated as well (Ottenheijm and Granzier, 2010; Fridén and Lieber, 2003)." (PMID 30565562, 2018). "However, the role of titin in modulating skeletal muscle stiffness has been of growing interest, revealing altered titin‐based stiffness in conditions such as cerebral palsy and Ehlers–Danlos syndrome." (PMID 39163874, 2024).
COVID-19 (2 papers, 2021 to 2023). A disease caused by infection with severe acute respiratory syndrome coronavirus 2. "Another publication stated that TTN is downregulated after IL-6 treatment, implying a corresponding downregulation in patients with COVID-19." (PMID 37109540, 2023). "As for the second parameter, TTN (ENSG00000155657), which was shown downregulated in this rule, was used in distinguishing patients with COVID-19." (PMID 37109540, 2023).
dystrophin deficiency (2 papers, 2025). "Serum titin/Cr was shown to be a biomarker to discriminate clinical severity in patients with dystrophinopathy." (PMID 40703779, 2025). "In this study, we measured the serum titin/creatinine (Cr) ratios in 110 patients with dystrophinopathy and compared them between patients with DMD and BMD with different clinical severities and unaffected controls to evaluate the discriminative ability of this measure." (PMID 40703779, 2025).
esophageal cancer (2 papers, 2025). A primary or metastatic malignant neoplasm involving the esophagus. "Preoperatively, urinary titin levels were 5.03 (3.05–8.51) pmol/mg Creatinine (Cr), which was slightly higher than in healthy subjects (1–3 pmol/mg Cr), particularly in patients with esophageal cancer (8.2 ± 3.1 pmol/mg Cr)." (PMID 40076646, 2025).
hyperthyroidism (2 papers, 2023 to 2024). Overactivity of the thyroid gland resulting in overproduction of thyroid hormone and increased metabolic rate. "The corresponding mutated genes set that has common effects on hyperthyroidism in children included IGF1, CACNA1S, MYH7, IL6, TTN, CACNB2, LAMA2, and DMD." (PMID 37876543, 2023).
interstitial lung disease (2 papers, 2023 to 2024). A diverse group of lung diseases that affect the lung parenchyma. "This study aimed to examine the validity of urinary N-terminal titin fragment/creatinine (urinary N-titin/Cr) reflecting muscle damage biomarker in patients with interstitial lung disease." (PMID 37322176, 2023).
ischemic cardiomyopathies (2 papers, 2019 to 2025). "Similarly, mutations in TTN, encoding the giant sarcomere protein titin, can also cause different types of structural, non-ischemic cardiomyopathies." (PMID 31489928, 2019). "Stratification by etiology revealed distinct functional characteristics, including enhanced contractile force in titin-mutant LMS and a positive force-frequency relationship in ischemic cardiomyopathy-derived LMS." (PMID 40799359, 2025).
laminopathies (2 papers, 2023 to 2024). "Titin (TTN) is recognized as the major candidate gene for DCM, with mutations in TTN accounting for a significant proportion of familial and idiopathic cases, and LMNA, known for its role in laminopathies affecting cardiac function." (PMID 39329103, 2024).
Left ventricular dilatation (2 papers, 2018 to 2020). Enlargement of the chamber of the left heart ventricle. "Transcriptional and post-translational changes that increase titin’s length and extensibility, making the sarcomere longer and softer, are associated with systolic dysfunction and left ventricular dilation." (PMID 32859027, 2020).
muscle degeneration (2 papers, 2025). "Therefore, in the present study, we examined whether creatinine kinase, similar to urinary titin, was associated with skeletal muscle atrophy after 6 months." (PMID 40076646, 2025). "In this study, we found that high levels of urinary titin on POD1 predicted long-term skeletal muscle atrophy following gastroenterological surgery." (PMID 40076646, 2025). "The levels of these products are >700- and >30-fold higher in patients with DMD and BMD, respectively, compared with healthy individuals, suggesting that urinary titin may be a biomarker for muscle degeneration." (PMID 40703779, 2025). "Therefore, the concentration of titin fragments in the blood may directly reflect the degree of muscle degeneration in DMD and BMD." (PMID 40703779, 2025).
muscular atrophy (2 papers, 2017 to 2025). "It will be interesting to determine whether ubiquitin ligases such as MURF1 and other tripartite motif-containing proteins are responsible for this gradient of titin ubiquitination; such studies will help us to understand the sequential order of protein degradation during muscular atrophy." (PMID 28546288, 2017).
neuropathy (2 papers, 2018 to 2021). A disorder affecting the nervous system that manifests with pain, tingling, numbness, and/or muscle weakness. "Three of these now have a confirmed genetic diagnosis (MYH7 and TTN genes in the neuropathy group and MYOT in the IBM group)." (PMID 29997562, 2018).
oral cancer (2 papers, 2024 to 2025). "Although the role of TTN in oral cancer is limited, in this study, our aim was to investigate the potential genetic polymorphisms of TTN in Taiwanese patients with oral cancer." (PMID 39337369, 2024).
rectal tumors (2 papers, 2024 to 2025).
renal carcinoma (2 papers, 2014 to 2025). A carcinoma arising from the epithelium of the renal parenchyma or the renal pelvis. "We found that classic renal cancer–related genes such as VHL, PBRM1, TTN, and SETD2 had higher mutation frequencies in the TCGA-KIRC cohort, with PBRM1 having a higher mutation rate in XPS1 compared to XPS2 (43% vs. 37%), while mTOR had a lower mutation rate in XPS1 compared to XPS2 (6% vs. 10%)." (PMID 39882192, 2025).
scleroderma (2 papers, 2021 to 2023). Scleroderma is a rare autoimmune connective tissue disorder characterized by abnormal hardening of the skin and, sometimes, other organs. "Mutated genes in this regard are associated with inherited hypertrophic cardiac muscle disease, and autoantigen against titin has been identified in patients with the autoimmunity illness scleroderma." (PMID 34746153, 2021).
scoliosis (2 papers, 2025). A congenital or acquired spinal deformity characterized by lateral curvature of the spine. "In this case report, we describe two sisters with severe scoliosis, both carrying novel compound heterozygous variants in the TTN gene, yet presenting distinct clinical phenotypes, adding to the growing body of evidence linking TTN mutations to scoliosis and other titin-related disorders." (PMID 39926328, 2025).
sudden cardiac arrest (2 papers, 2022 to 2025). Unexpected rapid natural death due to cardiovascular collapse within one hour of initial symptoms. "TTN missense mutations were identified in four of six unrelated patients with sudden cardiac arrest caused by PVF during STEMI." (PMID 41552678, 2025).
adenoma (1 paper, 2023). A neoplasm arising from the epithelium. "In the adenoma group, GNAQ, KRAS, MUC16, and TTN were identified as the driver genes, whereas in the cancer group, only GNAQ and KRAS were identified as the driver genes." (PMID 37546388, 2023).
Akinesia (1 paper, 2023). Inability to initiate changes in activity or movement and to perform ordinary volitional movements rapidly and easily. "In conclusion, TTN mutations should be considered for infants presenting with fetal akinesia and myopathy." (PMID 37497165, 2023).
alcohol abuse (1 paper, 2023). The use of alcoholic beverages to excess, either on individual occasions ("binge drinking") or as a regular practice. "It is emerging that genetic variants in TTN are enriched in cohorts of cardiac disease caused by pregnancy, alcohol abuse or cancer therapy, suggesting that an aggravated response to an environmental trigger could be caused by the presence of the TTN variant." (PMID 36935760, 2023).
amyloidosis (1 paper, 2016). A disorder characterized by the localized or diffuse accumulation of amyloid protein in various anatomic sites. "Cumulatively, our results indicate that titin may be involved in generation of amyloidosis in smooth muscles." (PMID 27129292, 2016).
amyotrophic lateral sclerosis (1 paper, 2024). Amyotrophic lateral sclerosis (ALS) is a neurodegenerative disease characterized by progressive muscular paralysis reflecting degeneration of motor neurons in the primary motor cortex, corticospinal tracts, brainstem and spinal cord. "Additionally, we show that the levels of both titin mRNA and protein are altered in the spinal cord of SOD1G93A mice, a commonly used model of amyotrophic lateral sclerosis, indicating that titin mediated nucleolar events may in fact contribute to the pathobiology of disease." (PMID 38496572, 2024).
Anorexia (1 paper, 2025). Lack of desire to eat (loss of appetite). "This may suggest that urinary titin levels are influenced by surgical invasiveness, leading to increased catabolism, which could contribute to anorexia in the early postoperative period and reflect changes in postoperative recovery from surgical invasiveness, particularly in skeletal muscle mass." (PMID 40076646, 2025).
aortic valve stenosis (1 paper, 2022). Aortic valve stenosis (AVS) is a condition characterized by narrowing of the heart's aortic valve opening. "The finding indicates the mutations TTN, NUP205, and NCOR2 can enhance the severity of aortic valve stenosis, a consequence of BAV." (PMID 36071494, 2022).
asthma (1 paper, 2021). "For example, genome-wide association studies have identified cardiac-related genes, including CTNNA3 (encoding α-T-catenin) and TTN (encoding titin), as a factor for the pathogenesis or exacerbation of asthma." (PMID 34867960, 2021).
astrocytoma (1 paper, 2022).
bladder urothelial carcinoma (1 paper, 2019).
brain tumors (1 paper, 2024). "In cohort B, most common diagnoses were neurodegenerative disorders in 9/39 (23.1%), brain tumors in 6/39 (15.4%) while most common detected antibodies were anti–titin (N10), anti-recoverin (N11), anti-Yo (N8) and all were detected in serum only." (PMID 38438516, 2024).
breast tumor (1 paper, 2015). "Since myostatin promotes apoptosis in breast tumor cells, the overexpression of Titin-Cap would be expected to strongly promote breast tumor proliferation." (PMID 26543765, 2015).
cardiac arrest (1 paper, 2020). Cessation of breathing and/or cardiac function. "Using WebGestalt algorithms, in the present case, the combination of MYBPC3, TTN, ACADVL, and RYR2 increased significantly the likelihood of cardiac arrest." (PMID 32101375, 2020).
cerebellar degeneration (1 paper, 2024). Degeneration of the cerebellum. "Finally, TPE in patients with PNS, including POEMS, cerebellar degeneration associated with Yo and Hu antibodies, anti-titin myasthenic syndrome, and seronegative PN neuropathy was ineffective and almost employed before the obtaining a definite diagnosis." (PMID 39051217, 2024).
cholesteatoma (1 paper, 2015). A pathologic process characterized by the proliferation of keratinizing squamous epithelium resulting in the accumulation of keratin and cells in the middle ear and/or mastoid. "Immunolocalization demonstrated that FKH 5–3 and titin were localized in the cell membrane and cytoplasm in all layers of congenital cholesteatoma keratinocytes." (PMID 26335306, 2015). "We found that titin matched the major spots found in proteomic analysis on congenital cholesteatoma samples and was also strongly expressed in cholesteatoma matrices, as shown with immunostaining." (PMID 26335306, 2015). "Another distinctive finding of our study was expression of titin in congenital cholesteatoma." (PMID 26335306, 2015). "Immunohistochemical staining showed that FKH 5–3 and titin were expressed in congenital cholesteatoma matrices, but not in acquired cholesteatomas." (PMID 26335306, 2015). "Moreover, non-epithelial proteins, including FKH 5–3 and titin, were unexpectedly expressed in congenital cholesteatoma tissue." (PMID 26335306, 2015).
clear cell renal cell carcinoma (1 paper, 2024). "For example, clear cell renal cell carcinoma (ccRCC) patients with von Hippel-Lindau (VHL) gene mutation showed a better survival trend compared with ccRCC patients with titin (TTN) gene mutation." (PMID 38256587, 2024).
Danon disease (1 paper, 2025). A lysosomal glycogen storage disease characterized by severe cardiomyopathy and variable degrees of muscle weakness, frequently associated with intellectual deficit. "The dilated phenotype subgroup (P.1–P.10) included all patients with Danon disease, the patient with a homozygous ALPK3 variant, carriers of in-frame deletions in TTN and FLNC, a heterozygous TRIM63 missense variant, and carriers of splice-site variants in MYH7 and MYBPC3." (PMID 41440877, 2025).
Desminopathy (1 paper, 2017). "A deviation from this pattern of titin protection by sHSPs was observed only in the single desminopathy patient studied by us." (PMID 28915917, 2017).
developmental delay (1 paper, 2019). "A majority of patients with TTN mutations have normal intelligence quotient (IQ), but our patients showed poor language development, mild microcephaly and developmental delay." (PMID 31664938, 2019).
esophageal squamous cell carcinoma (1 paper, 2021). Esophageal squamous cell carcinoma (ESCC) is a type of esophageal carcinoma (EC) that can affect any part of the esophagus, but is usually located in the upper or middle third. "Meanwhile, the level of LINC01711 in human healthy esophageal epithelial cell line HEEC and five esophageal squamous cell carcinoma cell line EC9706, Eca109, TE-13, TE-1, and TTN were analyzed by RT-qPCR." (PMID 34370713, 2021).
Ewing sarcoma (1 paper, 2023). A small round cell tumor that lacks morphologic, immunohistochemical, and electron microscopic evidence of neuroectodermal differentiation. "On the other hand, high expression of TTN and MYL3 genes can be described as a biomarker of a worse prognosis in Ewing’s sarcoma." (PMID 36982287, 2023).
filaminopathy (1 paper, 2017). "We set out to determine which chaperones associate with titin in muscle biopsies from different myopathies, including LGMD2A and MFM-filaminopathy." (PMID 28915917, 2017). "Collectively, these results suggest that sHSP-binding to elastic titin regions can increase the PT of the myofibers and explain, in part, the pathologically elevated PT of muscle cells found in LGMD2A and MFM-filaminopathy patients." (PMID 28915917, 2017).
gallbladder tumour (1 paper, 2022).
germ cell tumor (1 paper, 2022). A benign or malignant, gonadal or extragonadal neoplasm that originates from germ cells. "TTN mutation existed in mixed germ cell tumor and seminoma, and all of them were missense variant." (PMID 36713456, 2022).
gynecological cancers (1 paper, 2020). "Furthermore, TTN, MUC16, CSDM3, RYR2, USH2A, and SYNE1 were frequently mutated in gynecological cancers but not in the MSK-IMPACT samples, suggesting that they play specific roles in the development of gynecological malignancies." (PMID 32626534, 2020).
Hydrocephalus (1 paper, 2023). Hydrocephalus is an active distension of the ventricular system of the brain resulting from inadequate passage of CSF from its point of production within the cerebral ventricles to its point of absorption into the systemic circulation. "The phenotypic presentation of infantile hydrocephalus could be considered in children with mutations in the TTN gene." (PMID 37497165, 2023).
hypertensive heart disease (1 paper, 2016). Abnormal enlargement of the heart resulting from long-standing hypertension. "Notably, increased levels of collagen and reduced total-titin phosphorylation in DOCA pigs could be interpreted as a sign of a transition from hypertensive heart disease to HFpEF." (PMID 27688028, 2016).
injury (1 paper, 2024). Damage inflicted on the body as the direct or indirect result of an external force, with or without disruption of structural continuity. "Moreover, MMP-2 contributes to acute cardiac dysfunction through the degradation of intracellular contractile machinery proteins, such as troponin I (TnI), titin, myosin light chains 1 and 2 (MLC1 and 2) in oxidative-stress-induced-heart injury." (PMID 38540247, 2024).
kidney chromophobe carcinoma (1 paper, 2025).
left ventricular noncompaction (1 paper, 2016). Left ventricular noncompaction (LVNC) is a rare cardiomyopathy characterized anatomically by prominent left ventricular trabeculae and deep intratrabecular recesses causing progressive systolic and diastolic dysfunction, conduction abnormalities, and occasionally thromboembolic events. "Here we present genetic and functional evidence implicating the novel A178D missense mutation in titin as the cause of a highly penetrant familial cardiomyopathy with features of left ventricular noncompaction." (PMID 27625337, 2016).
malaria (1 paper, 2016). Malaria is a serious and sometimes fatal disease caused by a parasite that commonly infects a certain type of mosquito which feeds on humans. "Our results suggest that Superoxide dismutase, Vitronectin, Titin, Apolipoprotein E, Serum amyloid A, and Haptoglobin are potential predictive markers for malaria severity." (PMID 27090372, 2016). "Quite a few differentially abundant proteins such as Haptoglobin (HP), Superoxide dismutase (SOD), Ceruloplasmin (CP), Titin (TTN), Nebulin (NEB), and Vitronectin (VTN) were found to be highly relevant in context of pathophysiology of severe malaria." (PMID 27090372, 2016). "Interestingly, SAA, TTN, SOD and CP exhibited differential abundance (>1.5-fold up-regulated) between SVM and NSVM, indicating their potentiality as the predictive markers for malaria severity." (PMID 27090372, 2016).